ABHD15 (abhydrolase domain containing 15)
Description:
May regulate adipocyte lipolysis and liver lipid accumulation.
Tractability: Antibody: UniProt places it where antibodies can reach, with high confidence; UniProt predicts a signal peptide or a membrane-spanning region; its Gene Ontology location is reachable by antibodies, with medium confidence. PROTAC: ubiquitination databases record sites on it.
Gene: Protein-coding gene on chromosome 17 (29,560,547 to 29,567,037, reverse strand). Ensembl gene ENSG00000168792.
Subcellular location: Secreted
Subcellular location (Human Protein Atlas): Cytosol; Nucleoplasm; Predicted to be secreted
Gene Ontology:
Molecular function: protein binding; monoacylglycerol lipase activity; short-chain carboxylesterase activity
Biological process: adipose tissue development; lipid catabolic process; lipid metabolic process
Cellular component: membrane; extracellular region
Genetic constraint (gnomAD): Loss-of-function variants: 34 observed, 30.61 expected, observed/expected ratio (o/e) 1.11, 90% interval 0.84 to 1.48. The upper end of that interval is the gene's LOEUF score, 1.48, which puts it in group 6 of 6, group 1 being the genes least tolerant of losing a copy. Missense variants: 644 observed, 615.93 expected, observed/expected ratio (o/e) 1.05, 90% interval 0.98 to 1.12. Synonymous variants: 314 observed, 282.56 expected, observed/expected ratio (o/e) 1.11, 90% interval 1.01 to 1.22.
Homologues: Orthologues: chimpanzee ABHD15 (99% identical), macaque ABHD15 (96% identical), dog ABHD15 (89% identical), guinea pig ABHD15 (87% identical), rabbit ABHD15 (87% identical), mouse Abhd15 (86% identical), pig ABHD15 (86% identical), rat Abhd15 (85% identical), tropical clawed frog abhd15 (53% identical). Paralogues in human: ABHD1 (22% identical), ABHD3 (20% identical), ABHD2 (16% identical).
Diseases named in the same sentence as ABHD15 in open-access papers:
ABHD15 is named in the same sentence as 5 diseases in open-access papers, as found by Europe PMC text mining. Sharing a sentence is not in itself a finding about the gene and the disease. The quoted sentences say what the papers report.
Insulin resistance (3 papers, 2013 to 2023). Increased resistance towards insulin, that is, diminished effectiveness of insulin in reducing blood glucose levels. "In view of dysregulated lipolysis in the absence of ABHD15 observed in this study, it was of interest to determine whether ABHD15 was altered in insulin resistance." (PMID 31105056, 2019). "For these reasons it is tempting to speculate that reduction/impairment of “protecting Abhd15” by increased FFA content leads to induced apoptosis and its further consequences, like recruitment of adipose tissue macrophages, insulin resistance, and development of fatty liver." (PMID 24236098, 2013).
diabetes (1 paper, 2013). "Together with its intricate regulation by free fatty acids, ABHD15 might be an intriguing new target in obesity and diabetes research." (PMID 24236098, 2013). "Together with its intricate regulation by FFAs, Abhd15 might be an intriguing new target in obesity and diabetes research, as it impacts on adipogenesis and apoptosis, both factors crucially determining adipose cell number and size." (PMID 24236098, 2013).
non-alcoholic fatty liver disease (1 paper, 2019). "The absence of ABHD15 in combination with stress led to a marked increase in liver lipid levels due to hyperactive adipocyte lipolysis, highlighting the important role of adipocyte lipolysis in non-alcoholic fatty liver disease (NAFLD) and other liver defects." (PMID 31105056, 2019).
Obesity (1 paper, 2013). Accumulation of substantial excess body fat. "Additionally, we identified free fatty acids (FFAs) as negative regulators of Abhd15 expression in differentiated adipocytes as well as in physiological circumstances like in fasting or obesity." (PMID 24236098, 2013). "Interestingly, while Abhd15 expression increases during adipogenesis, it decreases in the presence of high levels of FFAs, as observed in diet- and genetically induced obesity, fasting and aging, as well as upon FFA treatment of cultured mature adipocytes." (PMID 24236098, 2013).
Simpson-Golabi-Behmel syndrome (1 paper, 2013). Simpson-Golabi-Behmel syndrome is a rare X-linked multiple congenital anomalies syndrome, characterized by pre- and postnatal overgrowth, distinctive craniofacial features, variable congenital malformations, organomegaly and an increased tumor risk. "A similar expression profile of the human ortholog of Abhd15 could be shown in Simpson-Golabi-Behmel syndrome (SGBS) cells." (PMID 24236098, 2013).